HOPX (HOP homeobox)
Diseases named in the same sentence as HOPX in open-access papers (continued):
Sharing a sentence is not in itself a finding about the gene and the disease.
tumor (continued). "HOPX protein was increased in nlsYAP5SA mice and in LATS1/2 cKO tumours." (PMID 32404936, 2020). "First, the degree of hypermethylation of the specific DNA promoter regions of the 4 methylation genes (CDO1, HOPX, Reprimo, and E-cadherin) was assessed in tumor tissues and the corresponding non-cancerous mucosa tissues in 58 RGC patients." (PMID 31069006, 2019). "HOPX promoter methylation was observed in a subset of HNSCCs and was associated with a worse overall survival in HPV negative tumours." (PMID 27934959, 2016). "In our LATS1/2 cKO mouse model, although some of the tumour markers were highly present in the centre of the tumour mass, e.g., ANKRD1, Vimentin, CK18, nestin and Ki67, some were localised towards the edges of the tumour, e.g., HOPX, AMOTL2, AXL and microglial marker C3." (PMID 32404936, 2020). "The divergent expression of HOPX in the TME across different tumor types might be due to several factors, including alterations of tumor cells and stromal cells driven by genetic and epigenetic mechanisms, as well as complex interactions of tumor cells with immune cells and fibroblasts." (PMID 41227363, 2025). "Consistent with this, we did not see a difference in RASSF1 expression in tumor samples defined by EBV status, but there was a significantly lower expression of HOPX in EBV+ tumors." (PMID 41280003, 2025). "Before injecting the cells into mice, we conducted proliferation and self-renewal assays in vitro to ensure that ANXA1-KO, HOPX-KO, and RFX4-KO cells exhibited no discernible advantages in growth or tumor-forming capabilities." (PMID 40683881, 2025). "ND GBM pre-surgery saliva (NDT0) showed the exclusive characterization of peptide fragments of CDA, HOPX, FABP5, WIPF3, VOPP1, AHNAK, and DAZAP1 proteins, which, to the best of our knowledge, have not been previously identified in relation to GBM tumor." (PMID 41155285, 2025). "TaqMeth Vs were significantly higher in the tumor tissues than in the corresponding non-cancerous mucosa tissues for CDO1 (P < 0.0001), HOPX (P < 0.0001), and Reprimo (P = 0.0006), except for the E-cadherin (P = 0.08)." (PMID 31069006, 2019). "In contrast, we did not observe an upregulation of C1QL1 in HOPX+ embryonic hNSCs during human hippocampal development, which also underwent neurogenic-to-gliogenic switch, suggesting that the upregulation of C1QL1 is tumor-specific and may promote tumorigenesis." (PMID 33390587, 2021).
cancer (29 papers, 2012 to 2025). A tumor composed of atypical neoplastic, often pleomorphic cells that invade other tissues. "The mechanism of HOPX inactivation is essentially caused by promoter DNA methylation in human cancers." (PMID 31934721, 2020). "Collectively, epigenetic silencing of HOPX expression caused by the promoter methylation is critically involved in cancer progression and patient prognosis in PTC." (PMID 31666923, 2019). "Despite substantial evidence indicating that HOPX is associated with multiple cancers, the mechanism of HOPX in cancer remains elusive." (PMID 28146149, 2017). "Therefore, HOPX expression levels might be associated with increased sensitivity of cancer cells to clinical drugs and prolonged survival of cancer patients, suggesting its potential as a marker for personalized treatment selection in the clinic." (PMID 37344870, 2023). "Under cancerous conditions, increased HOPX was detected in CD4+ and CD8+ T cells, and HOPX overexpression in cancer cells is significantly related to CD8+ T cell infiltration in the TME." (PMID 41227363, 2025). "It is important to note that HOPX over-expression is involved in suppression of cancer cell proliferation and metastasis." (PMID 35538578, 2022). "HOPX hypermethylation directly results in gene silencing of HOPX, especially the HOPX-β promoter hypermethylation containing CpG islands that are methylated in various cancers leading to down-regulation of HOPX expression." (PMID 31934721, 2020). "EGR-1 is a downstream transcription factor of HOPX that controls cancer progression through induction of IGF-II, PDGF, and TGF-β." (PMID 31934721, 2020). "Epigenetic silencing of HOPX via its promoter methylation has been shown frequent and cancer-specific in human cancers." (PMID 31666923, 2019). "Further insights into the detailed mechanism of HOPX silencing in cancer progression are likely to provide a clue to tackle PTC with treatment refractoriness." (PMID 31666923, 2019). "Immunohistochemistry of Ki-67 supports that hypermethylation of HOPX leads to more cancer cell proliferation in patients with PTC." (PMID 31666923, 2019). "HOPX promoter methylation is frequent and cancer-specific event, leading to aggressive phenotype in PTC." (PMID 31666923, 2019). "We have recently identified HOPX as genes specifically methylated in human cancers after developing algorithm utilizing pharmacological unmasking microarray (PUM)." (PMID 22958219, 2012). "Collectively, we found that HOPX methylation is a very frequent and cancer specific event in PC development." (PMID 22958219, 2012). "DNA hypermethylation of HOPX with gene silencing is therefore likely to affect PC phenotypes as in other cancers." (PMID 22958219, 2012). "Allowing for actual expression in primary cancer tissues, constitutive HOPX expression signal was derived from carcinoma-stroma interaction in primary PC cells." (PMID 22958219, 2012). "Again, this may reflect the complex and context-dependent functions of HOPX in cancer development and therapy response." (PMID 41227363, 2025). "The downregulation of HOPX expression contributes to colorectal, head, neck and other cancers." (PMID 38110859, 2023). "Indeed, enforced expression of HOPX suppress cell proliferation, invasive activities, and anchorage-independent growth that reflects metastatic potential of cancer cells." (PMID 31666923, 2019). "Epigenetic silencing of HOPX may be a clue to tackle cancer progression and have clinical impact as a novel biomarker in PTC." (PMID 31666923, 2019). "HOPX is a transcription factor epigenetically silenced in several cancers." (PMID 28146149, 2017). "Specifically, the expression of HOPX is suppressed in various primary cancer tissues." (PMID 24287901, 2013). "The expression of HOPX is marked suppressed in a subset of cancers, mainly in an epigenetic manner." (PMID 24287901, 2013). "HOPX expression is markedly suppressed in a subset of cancers, mainly in an epigenetic manner." (PMID 24287901, 2013).
cancer (continued). "It is intriguing hypothesis that cancer cell with low expression of HOPX is derived from islet cells which constitutively express abundant HOPX, and that promoter DNA hypermethylation is causative for gene silencing." (PMID 22958219, 2012). "On this ground, we speculate that the same program that regulates the regeneration of keratinized epithelia may be aberrantly activated in CRC by HOPX overexpression, thus committing cancer cells toward an aggressive phenotype with traits of epithelial cornification." (PMID 37079732, 2023). "The HOPX gene may be involved in the malignant transformation of cancer cells." (PMID 33758613, 2021). "Conversely, HOPX overexpression could suppress cancer proliferation and metastasis." (PMID 31934721, 2020). "Also, HOPX was correlated with genes in a manner toward suppression of cancer cell progression; downregulation of TNRC6C, PAX8, TSHR, DYRK1A/B, and SLIT3 (pro-proliferation/migration), and upregulation of PCDH8/9, CDC42EP3/4/5, and TJP3 (anti-proliferation/migration)." (PMID 31666923, 2019). "Furthermore, HOPX is involved in multiple functions of cancer cell progression." (PMID 31666923, 2019). "However, little is known regarding the mechanism of HOPX in cancer or its correlation with NPC." (PMID 28146149, 2017). "However, there have been few reports describing downstream genes of HOPX in human cancers." (PMID 24287901, 2013). "However, the mechanism by which HOPX represses target genes in human cancer is unknown." (PMID 28146149, 2017). "In human cancer cells such as HEC and MCF7, forced expression of HOPX resulted in a partial block in cell proliferation, in vivo tumorigenicity, and c-fos gene expression in response to 17 beta estradiol (E2) stimulation." (PMID 24287901, 2013). "Neither cancer cells nor normal pancreatic components such as acinar and ductal cells showed staining of HOPX." (PMID 22958219, 2012). "Additionally, the inhibition of glucose metabolism failed to induce HOPX expression despite the effective suppression of cancer organoid growth." (PMID 41227363, 2025). "Nevertheless, in the context of tumors, HOPX might facilitate the rapid enrichment of CD8+ T cells, neoantigen-reactive CD4+ T cells, and possibly their corresponding receptors within the TME, which in turn boosts the immune system to combat cancer." (PMID 41227363, 2025). "A novel theoretical foundation for cancer management against GC is the restoration of intestinal microbial butyrate, which increases CD8+ T-cell cytotoxicity through hydroxycarboxylic acid receptor 2 (HCA2), also known as GPR109A/HOP homeobox (HOPX) and inhibits GC carcinogenesis." (PMID 38730659, 2024). "PITX1, CST6 and HOPX were reported their downregulation in various types of human cancer, and PRSS27 was known to be highly expressed in nonkeratinizing stratified squamous epithelia of human esophagus and its dysregulation was supposed to be related to characteristics of carcinoma." (PMID 29137437, 2017). "HOPX may be involved in cell invasiveness in CRC and other cancers." (PMID 24287901, 2013). "However, the mechanism of HOPX in human cancer has not yet been clear." (PMID 31934721, 2020). "In this current study, several CAFGs—VIM, ANXA1, HOPX, CALD1, and COL8A1—were confirmed highly expressed in TC cells, but not in those of other cancers (except ANXA1 in PDAC)." (PMID 41228323, 2025).
adenocarcinoma (2 papers, 2019 to 2020). A common cancer characterized by the presence of malignant glandular cells. "HOPX hypermethylation also tended to be associated with HP infection in both RGC and RN (P = 0.06 and P = 0.1), suggesting that HOPX methylation with its gene silencing may play a critical role in HP-induced intestinal metaplasia-adenocarcinoma sequence." (PMID 31069006, 2019). "The expression of a second adenocarcinoma differentiation marker, SFTPC, was significantly reduced by AdSLFN12 treatment in only one LUAD cell (HCC827), while AdSLFN12 significantly reduced HOPX mRNA levels in two LUAD cells (HCC827 and H23) with no significant changes in LUSC cells." (PMID 32987632, 2020).
cardiac disease (1 paper, 2025). "The involvement of HDAC2 in cardiac disease was initially identified as acontributing factor to hypertrophy derived from the “homeodomain-only protein”(HOPX)." (PMID 40776938, 2025).
infection (1 paper, 2014). The state of being infected such as from the introduction of a foreign agent such as serum, vaccine, antigenic substance or organism. "We were unable to detect any significant differences in GFAP or HOPX staining between GFP and NFIX infections." (PMID 24848099, 2014). "Expression of the early astrocyte marker CD44 increased ∼2-fold with both HOPX and NFIX overexpression in fetal astrocytes (assayed three days post-infection)." (PMID 24848099, 2014).
HOPX also shares sentences with these, for which no sentence is quoted: acute myeloid leukemia (3 papers); hepatocellular carcinoma (3); acute lymphoblastic leukemia (1); Arthritis (1); bladder cancer (1); colorectal tumor (1); diabetes mellitus (1); diabetic cardiomyopathy (1); epilepsy (1); esophageal cancer (1); gastric tumors (1); left ventricular hypertrophy (1); lung squamous cell carcinoma (1); metabolic syndrome (1); neurodegenerative disease (1); pancreatic neuroendocrine tumor (1); prostate adenocarcinoma (1); squamous cell carcinoma (1); squamous skin cell carcinoma (1); stomach adenocarcinoma (1); Type 2 Diabetes (1); uveal melanoma (1).